PDGFRA (platelet derived growth factor receptor alpha)
Diseases named in the same sentence as PDGFRA in open-access papers (continued):
Sharing a sentence is not in itself a finding about the gene and the disease.
tumor (continued). "Mutational analysis did not reveal any mutation in PDGFRα or KIT, and suggested the possibility of a low-grade tumor other than GIST." (PMID 27842558, 2016). "On the other hand, the expression of CD166, CD133, CD44, A2B5, CD56, NGFR and DCX seemed to be higher in UA cells, but also not statistically significant, while the expression of CD9, Nestin, GFAP, CD24, PDGFRb, PDGFRa, MAP2, TUBIII, S100 were consistently high in both UA and tumor core samples and." (PMID 27605047, 2016). "Endoxifen-induced tumours expressed GFAP, nestin, Sox2, Olig2, PDGFRa and doublecortin (Fig. 5E1-J1), and were indistinguishable from tumours generated by Adeno-Cre or Adeno-GFAP-Cre injection and as shown in Fig. 5E2-J3." (PMID 26704996, 2016). "By contrast, tumor size in Group A patients was greater (10.1 ± 5.8 cm) than in Group B (4.7 ± 1.9 cm; p = 0.0002), whereas the frequency of the WT status for both KIT and PDGFRA was lower in Group A than B (14.3 % vs. 50 %; p = 0.009)." (PMID 26867653, 2016). "Surprisingly, co-localization of PDGFRα and PDGFRβ in T241 tumours by their specific antibodies showed that TAMs lacked PDGFR expression, suggesting an indirect role of PDGF-BB in the recruitment of TAMs." (PMID 27150562, 2016). "Immunohistochemically, the tumor cells were positive for vimentin and cluster of differentiation 34, while they were negative for keratin, PDGFRA, smooth muscle actin, desmin, S-100 protein, DOG-1 and c-kit." (PMID 25435986, 2015). "In RMS, major characteristic of tumour aggressiveness is represented by the PAX3/7-FOXO1 fusion gene, a negative prognostic factor that regulates transcription of several downstream tumour-driving genes, including c-Met, CXCR4, FGFR4, IGFR-1R and PDGFRα kinases." (PMID 26147305, 2015). "In contrast, no tumor regression, even not in the combination with irradiation, was found in the non-amplified PDGFRA NEM14, which in general responded less well to treatments compared to the other two models." (PMID 26599335, 2015). "In the case of the mutant PDGFRα proteins, we observe a strong and long lasting activation of STAT1, STAT3 and STAT5, which will undoubtedly have a much more prominent effect on the cells and/or the tumour microenvironment." (PMID 25880691, 2015). "In contrast, mutations in PDGFRA and PTEN developed later in tumor progression, finding that not all biopsy tumor fragments expressed these aberrations." (PMID 25411563, 2014). "None of the PDGFRA gains/amplifications, PIK3CA mutations, ALT phenotype or ACVR1 mutations were found in tumours with PNET histology." (PMID 25047029, 2014). "When RTK expression was adjusted for known tumor characteristics, the significant correlations for c-KIT and VEGFR2 expression were retained whereas the association between PDGFRα and TNBC was not significant." (PMID 25025175, 2014). "Moreover, PDGFRα and PDGFRβ expression was detected by western blot in TGT44 tumors, confirming that these two pazopanib targets were also present in the tumor." (PMID 23937707, 2013). "Immunostaining for ASMA, PDGFRα, and FSP1 revealed that each of the CAF markers is expressed by spindle-shaped stromal cells infiltrating into the mass of epithelial cells already at this early stage of tumour development." (PMID 22432595, 2012). "PDGFRα overexpression in the presence of increased PDGF-CC led to increased Tyr720-PDGFRα in tumor bearing KO but not WT livers after DEN/PB." (PMID 22761897, 2012).
tumor (continued). "A kinase inhibitor targeting PDGFRA and/or FGFR or other frequently activated tyrosine kinases that can reach effective intra-tumor concentrations before dose limiting toxicity is a likely candidate for a combination with an EGFR inhibitor for a potentially more effective therapy." (PMID 23056179, 2012). "The corresponding proteins, namely PDGFRα, c-Kit and vascular endothelial growth factor 2 (VEGFR-2), play a central role in cancer biology and have been reported with genetic alterations and strong expression in a number of tumor entities." (PMID 20686603, 2010). "Tumour cell positivity is characteristic for calponin, MDM-2 and PDGFRα." (PMID 19830228, 2009). "Fifteen and eleven tumours possessed mutations in KIT and PDGFRA, respectively; no mutation was found in three tumours." (PMID 19943934, 2009). "In a random series of 110 HCC patients, the mRNA of HIF-1alpha, inflammation related factors (COX-2, MMP7 and MMP9), angiogenesis related factors (VEGF and PDGFRA) and MYC in tumor tissue were detected by real-time RT-PCR and HIF-1alpha protein was assessed by immunohistochemistry." (PMID 19948069, 2009). "While tumours lacking variants in these genes but also BRAF/RAS and NF1 have been dubbed ‘quadruple wild-type’, it is more appropriate to specify those genes that have been tested, e.g. WT for KIT, PDGFRA, NF1 and BRAF/RAS." (PMID 38840030, 2025). "Specifically, in FOXL2+COL1A1− cells, we examined expression of other AGCT tumor markers such as SF1, calretinin, and inhibinα, whereas in FOXL2+COL1A1+ cells, we also examined expression of stromal markers, including αSMA, vimentin, S100A4, PDGFRa, PDGFRb, and FAP." (PMID 41042551, 2025). "In the RGNT samples, compared with the non-tumour regions, strong stainings of OLIG2, SOX10, NG2 and PDGFRA were observed in the neurocytic regions in all samples analysed, and the astrocytic regions of the same samples showed sporadic and weaker expression of OLIG2, SOX10, NG2 and PDGFRA." (PMID 38764775, 2024). "In addition, the strong involvement of the PDGFA/PDGFRα axis in promoting the epithelial–mesenchymal transition (EMT) of HCC, as confirmed by several in vivo studies, further supports the correlation between its altered signaling and tumor metastatic capacity." (PMID 38473265, 2024). "In the human PDAC patient tumor transcriptome (TCGA), we identify strong and significant correlations between tumoral GHR expression and known lymphangiogenic (LYVE1, FLT4, VEGFC, and PDPN) and angiogenic (PDGFRa, FGFR1, TGFB3, TGFB1, TGFBR2, HIF1a, IL6, and IL1B) markers." (PMID 39000545, 2024). "To begin to determine what might be the role of CCN1 expression by CAFs, we used CAF single-cell expression data to identify a group of six genes (PDGFRA, COL1A1, DCN, TAGLN, COL6A3, and LPAR1) that strongly correlated with CCN1 expression, yet were minimally expressed in other tumor cell types." (PMID 38363129, 2024). "Notably, we found that xenografts only formed from the recurrent tumor harboring the gain of PDGFRA and amplification of CDK4 and MDM2, which were not identified in the initial tumor." (PMID 38012788, 2023). "Additionally, we observed that mATC cells overexpressed receptors such as FGFR1, EPHB2, PDGFRA, NOTCH3, ANTXR1, and NRP1, which could receive signals from CAFs and thereby promote tumor cell proliferation and aggressiveness." (PMID 37053016, 2023). "In addition, 1 patient with PDGFRA D842V mutation got 8.5 months PFS and no tumor progression happened and 3 patients with SDHB-deficient GIST had average of 16 months PFS." (PMID 36779523, 2023). "The GPA combination without PDGFRA was unable to drive tumor development." (PMID 37011011, 2023). "Furthermore, analyses of PDGFRA and PDGFRB expression in pancancer tissues additionally demonstrated that the reduction of PDGFRA and PDGFRB at both mRNA and protein levels in tumor tissues might be a common event, as elucidated by previous studies." (PMID 36199822, 2022).
tumor (continued). "To comprehensively characterize PDGFRA CN gain, we collected the CNV data and clinical information of pan-cancer patients from the TCGA database, systematically analyzed functional status of the tumor cells, and quantified the components of immune cells in the tumor immune microenvironment." (PMID 35212838, 2022). "Consequently, we detected PDGFRA gain in 11 tumor samples (10.3%) and PDGFRA amplification in 20 tumor samples (18.7%); the remaining 76 samples (71.0%) harbored no PDGFRA gain/amplification." (PMID 35911637, 2022). "Similarly, in H1703 NSCLC cells with PDGFRA amplification that are moderately sensitive/resistant to imatinib, bypass RTK activation is suppressed by prednisolone, and prednisone plus imatinib synergistically block tumor growth." (PMID 34853306, 2021). "Interestingly, depletion of MAP3K3, known to promote ovarian and NSCLC tumor growth, inhibited PDGFRA mutant GIST cell viability; however, no selective small molecule inhibitors are currently available to explore targeting MAP3K3 in GISTs." (PMID 33320833, 2021). "Interestingly, a recent report evaluated PDGFRα, PDGFRβ and PDGF-CC expression of tumor and/or stromal cell in primary tumors (N = 489), synchronous lymph node metastases (N = 135) and asynchronous recurrences (N = 39) using immunohistochemistry in a prospectively maintained cohort of BC patients." (PMID 34885027, 2021). "The tumours were analysed via flow cytometry for the simultaneous expression of six CAF markers: alpha smooth muscle actin (αSMA), fibroblast activation protein alpha (FAPα), platelet derived growth factor receptor alpha and beta (PDGFRα and PDGFRβ), CD26/DPP4 and podoplanin (PDPN)." (PMID 34016130, 2021). "Interestingly, the YFP+ tumor cells colocalized extensively with PDGFRα but not with GFAP or the neuronal marker NEUN." (PMID 32573857, 2020). "Unfortunately, different efforts could not establish PDGFRA as a reliable marker, as it is heterogeneously expressed in the stromal component of the tumour microenvironment and the tumour itself." (PMID 31996176, 2020). "Furthermore, YA patients significantly more often had non-KIT/PDGFRA positive tumours than patients in the OA group (25% vs. 11%, respectively; p = 0.008)." (PMID 32244864, 2020). "Importantly, although our mouse models identify Prrx1-expressing cells as a source of FUS-CHOP-driven tumors, cells expressing PdgfRα cannot be ruled out as a potential tumor-initiating cell for FUS-CHOP-driven tumors." (PMID 31427882, 2019). "Moreover, a hypothetical interaction of the anti-PDGFRA antibody with immunocompetent cells in tumor and/or stroma can also not be assessed in these immunodeficient animal models." (PMID 31331295, 2019). "Therefore, we suggest that other factors or pathways support tumor growth, but not metastasis, in the absence of PDGFRα/SDF-1 signaling activity." (PMID 30874597, 2019). "Although inhibition of PDGFRα reduces Sdf1 expression, no significant alterations in tumor cell proliferation or tumor growth were observed following pharmacological or genetic inhibition of PDGFRα in PD/S-SCCs, in agreement with that described after SDF-1 knocking-down." (PMID 30874597, 2019). "Only 2 tumours had high expression of PDGFRβ and PDGF-CC in combination with absent or low expression of PDGFRα (in both stromal and tumour cells), whereas 42 tumours had high expression of PDGFRα (in stromal and/or tumour cells) and PDGF-CC in combination with low PDGFRβ." (PMID 29380207, 2018). "Indeed, simultaneous detection of the vCAF marker Nidogen-2, the mCAF marker PDGFRα, and the dCAF marker SCRG1, identified three distinct stromal populations with divergent growth patterns and localization in relation to the nests of tumor cells." (PMID 30514914, 2018). "In addition, expression of PDGFRα on tumor sites had no relation with appearance of PDGFRα on reciprocal non-tumor sites." (PMID 28465473, 2017).
tumor (continued). "However, increased tumor site PDGFRα appeared to have no relation with non-tumor site PDGFRα, Col1α(I), and αSMA expression." (PMID 28465473, 2017). "Tumor cells with EGFR amplification, those in the process of migration or exposed to hypoxia all have been shown to express higher levels of ZEB1 than controls and experimental studies have identified molecular mechanisms involved in ZEB1 regulation, such as PDGFRA, Wnt- or TGF-beta signaling." (PMID 28945795, 2017). "Following expansion, flow cytometric analysis revealed the presence of PDGFRα (CD140a) and PDGFRβ (CD140b) on tumor-derived Lin-EpCAM-CD73+CD90+ mesenchymal cells and their normal counterparts, as well as human lung fibroblasts (HLFib) and bone marrow-derived MSCs (BM-MSC)." (PMID 28878242, 2017). "Indeed, depending on the tumor genotype, about half to three quarters of patients with advanced GIST respond to treatment with anti-KIT/PDGFRA tyrosine kinase inhibitors (TKIs) including the first-line drug, imatinib mesylate (Novartis Pharmaceuticals, Switzerland)." (PMID 27793025, 2016). "The tumor cells were positive for PDGFRα and negative for KIT, DOG1, CD34, S100, and desmin." (PMID 27842558, 2016). "While numerous markers, such as PDGFRα, periostin and fibroblast activation protein (FAP) have been reported to identify CAF within the tumor microenvironment, SMA is most commonly used to identify those CAF with an ‘activated’ tumor-promoting myofibroblastic phenotype." (PMID 27992856, 2016). "In addition, PDGFRA knockdown using a specific siRNA suppressed the viability of GIST-T1 cells, suggesting the tumor suppressive effect of miR-34a may be mediated at least in part through targeting PDGFRA." (PMID 26214687, 2015). "However, some rare tumours, including LSCC, that demonstrate PDGFRA activation may also be clinically responsive to pharmacologic PDGFRA inhibition." (PMID 26373952, 2015). "Finally, PDGFRA could be predicted by T2-FLAIR hyperintensity/total tumor volume (AUC = 0.72, p = 0.026) and tumor bulk/total tumor volume ratios (AUC = 0.72, p = 0.026)." (PMID 26337765, 2015). "Given the absence of activating missense mutations that confer sunitinib sensitivity, the amplification of KIT, PDGFRA, and/or VEGFR2 may have represented the critical sunitinib target in our case and may explain the primary good response of the tumor to the drug." (PMID 26474454, 2015). "Off target efficacy resulting from inhibition of angiogenic kinases in addition to FGFR2 inhibition could explain the anti-tumor activity exhibited in patient 6, as pazopanib has been shown to have nanomolar range potency towards VEGFR1-3, PDGFRA/B and CKIT as well." (PMID 24550739, 2014). "This was not a reflection of tumor purity, as all mutation-negative specimens had comparable tumor cellularity by histopathologic assessment (80-95%) and identical allele fractions of common SNPs in FGFR3 and PDGFRA (≥99%, data not shown)." (PMID 25523272, 2014). "Patients with a significant (>1+) increase in PDGFRα expression after treatment with BRAF-I +/- MEK-I had less tumor regression and shorter time to disease progression (P=0.07) when compared to patients who had no change or a small change in PDGFRα expression (≤1+)." (PMID 24732172, 2014). "In this study, we showed that treatment of GIST xenograft lines with nilotinib resulted in a decrease in tumor growth, suggesting that nilotinib-mediated growth inhibition in GIST might be occurring through interference with the activity of KIT or PDGFRA signaling pathways." (PMID 25221952, 2014). "This tumor had amplification of PDGFRA and KIT in region A not detected within other regions." (PMID 25608559, 2014).
tumor (continued). "Taken together, S116836 may have clinical efficacy against human neoplasms driven by FIP1L1-PDGFRα and other forms of activated PDGFRα regardless of the mutation status." (PMID 25431951, 2014). "Type 1 GISTs usually occur in adults with no predilection of tumor's locations, show homogeneous M/F, present KIT or PDGFRA mutations, and, generally, may benefit from the imatinib treatment." (PMID 24386562, 2013). "Interestingly, phosphorylation of these receptors was not documented using the phospho-RTK array, indicating that while expressed, PDGFRα/β is likely not driving tumor growth and survival through constitutive activation." (PMID 22630170, 2012). "Of note, none of these tumor stem cells cultures, showed PDGFRA overexpression or amplification." (PMID 22389665, 2012). "Thus, cells expressing ASMA and PDGFRα were located in fibrotic streaks and displayed a spindle-shaped morphology, whereas FSP1+ cells were distinguished by a rounded shape and located both in the overt stroma and within tumour cell clusters." (PMID 22432595, 2012). "NB-FOXR2 tumors are not the only tumor type to be associated to a cortical interneuron lineage; H3.3G34R/V HGGs originate in GSX2+ interneuron progenitors, and the chromatin state at the GSX2 locus in this cell context underlies the vulnerability to PDGFRA alterations." (PMID 39495206, 2025). "Importantly, PDGFRA, known as the core regulator of angiogenesis, was the only TG that showed a negative correlation with OS at both the mRNA and protein levels, suggesting that HMGB1 might drive patients’ poor prognosis by promoting tumor angiogenesis." (PMID 39039072, 2024). "An exploratory study of the NAVIGATOR trial for PDGFRA-mutant GIST showed that mutant ctDNA was detected in 63% of patients, and in this same population, the median sum of target lesions was 18.2 cm, suggesting that ctDNA detection might be potentially limited by the tumor burden." (PMID 37232809, 2023). "Importantly, in contrast to previously published H3K27M-driven models, the models described here are the first and only brainstem-targeted models that do not rely on constitutively active PDGFRA or PDGF overexpression to drive tumor development while maintaining high penetrance." (PMID 37011011, 2023). "Moreover, we found that in most cancers, tumor-infiltrating immune cell subsets, especially the effector immune cell subsets such as Activated CD8 T cell, Effector memory CD8 T cell, Activated B cell, and Immature B cell are less abundant in the group of PDGFRA pathway CN gain." (PMID 35212838, 2022). "Interestingly, molecular analysis review conducted on tumor samples with the new v12.3 classifier showed a match with pediatric RTK1 type, subtype B, and a complex copy number variation (CNV) with CDK6 and MET amplification, and a platelet-derived growth factor A (PDGFRA) gain." (PMID 35204463, 2022). "To explore tumor stage‐associated genes, we discovered that the correlation of expression for PDGFRA and SOX17 in neighboring cells is higher in early‐stage tumor patients but not in late‐stage patients." (PMID 40420636, 2026). "In our analysis, although we sampled only a fraction of the tumor, the similar cell age estimated for MDM4+/EGFR+ and MDM4+/PDGFRA+ clones suggested that neither of these clones gained selective advantage during tumor growth." (PMID 38724668, 2025). "Regarding EFS, only tumor site (p=0.015) reached statistical significance while stage III-IV (p=0.05), c-Kit (p=0.16), VEGFR2 (0.29), PDGFRα (p=0.0.25) or PDGFRβ expression (p=0.8) failed to reach statistical significance." (PMID 39534097, 2024). "Tumor profiling in GISTs is not performed routinely for patients outside of testing for KIT and PDGFRA." (PMID 38885448, 2024). "Analysis of region 3 investigating cycling (K) and noncycling (T) tumor cells revealed immense cellular heterogeneity, especially in the progenitor tumor cell phenotype and EGFR, NF1, and PDGFRA gene expression." (PMID 38077210, 2023).